INAFM1 (InaF motif containing 1)
Synonyms: PRR24
Tractability: Antibody: UniProt predicts a signal peptide or a membrane-spanning region.
Gene: Protein-coding gene on chromosome 19 (47,274,373 to 47,277,755, forward strand). Ensembl gene ENSG00000257704.
Subcellular location: Membrane
Gene Ontology:
Cellular component: membrane
Genetic constraint (gnomAD): Loss-of-function variants: 11 observed, 5.98 expected, observed/expected ratio (o/e) 1.84, 90% interval 1.05 to 1.96. That is too few expected variants to judge how well the gene tolerates losing a copy. Missense variants: 318 observed, 180.14 expected, observed/expected ratio (o/e) 1.77, 90% interval 1.61 to 1.93. Synonymous variants: 161 observed, 92.92 expected, observed/expected ratio (o/e) 1.73, 90% interval 1.52 to 1.94.
Homologues: Orthologues: chimpanzee INAFM1 (99% identical), dog INAFM1 (87% identical), mouse Inafm1 (69% identical), guinea pig INAFM1 (68% identical).
Diseases named in the same sentence as INAFM1 in open-access papers:
INAFM1 is named in the same sentence as 1 disease in open-access papers, as found by Europe PMC text mining. Sharing a sentence is not in itself a finding about the gene and the disease.
INAFM1 shares sentences with these, for which no sentence is quoted: cancer (1 paper).